GCG (glucagon)
Diseases named in the same sentence as GCG in open-access papers (continued):
Sharing a sentence is not in itself a finding about the gene and the disease.
Hyperglycemia (continued). "Thus, TD (a lipophilic form of vitamin B1) can improve hyperglycemia, which contributes to increased endogenous insulin secretion and decreased glucagon secretion." (PMID 35725834, 2022). "The suppression of glucagon secretion during hyperglycemia remains only partially understood." (PMID 36686477, 2022). "Thus, it is unlikely that glucagon-mediated stimulation of liver gluconeogenesis plays a primary role in the observed hyperglycemia in FSD MORF1 males." (PMID 35102183, 2022). "However, the increase in glucagon release due to STZ-induced hyperglycemia was significantly lower in the OMPlox/lox;GCGcre/w mice than in the wild-type OMPlox/lox mice." (PMID 36104518, 2022). "Many aspects of glucagon-secretion (e.g., in hyperglycemia) are still incompletely understood." (PMID 36686477, 2022). "Therefore, the improvement of hyperglycemia in the D-TD group reduced the effect of glucagon on hepatic glucose production." (PMID 35725834, 2022). "Cross‐ApEn was used to measure pattern reproducibility in the two hormones using glucagon as control mechanism (0.78 ± 0.03 vs. 0.76 ± 0.03, fasting vs. hyperglycemia) and using insulin as a control mechanism (0.78 ± 0.02 vs. 0.76 ± 0.03, fasting vs. hyperglycemia)." (PMID 35822422, 2022). "High glucagon levels are thought to be a major contributor to hyperglycemia in diabetics." (PMID 36273126, 2022). "GLP-1 RAs also suppress postprandial glucagon secretion to reduce hyperglycemia." (PMID 36559020, 2022). "Both zebrafish and mouse models of islet miR-21 induction displayed reduced expression of transcription factors specifying β-cell identity and in insulin+ cells, with increases in double positive insulin+ and glucagon+ islet cells, and hyperglycemia or glucose intolerance." (PMID 34246804, 2021). "Since the SSTR2a elicited a minor increase in glucagon concentrations during hyperglycemia in the perfused pancreas, it could be speculated that α cell–derived GLP-1 would be released in parallel, which could stimulate insulin release." (PMID 33434183, 2021). "Basal hyperglycemia occurs when there is a lower insulin-to-glucagon ratio owing to the increased production of glucose by the liver, whereas postprandial hyperglycemia arises due to a decrease in plasma insulin concentration or action that reduces glucose utilization in peripheral tissues." (PMID 34203830, 2021). "Persistent exposure to glucagon creates an excessive burden on liver due to ongoing gluconeogenesis and glycogenolysis, which in turn exacerbates hyperglycemia and eventually creating a vicious cycle, contributing to pathological condition known as insulin resistance." (PMID 34319011, 2021). "On the other hand, high protein in the diet could delay glucose response and potentially result in hyperglycemia by affecting gluconeogenesis, increasing glucagon secretion and impairing insulin’s ability to suppress endogenous glucose production." (PMID 33918343, 2021). "Failure to suppress glucagon secretion contributes to hyperglycemia in both T1D and T2D36." (PMID 34012065, 2021). "Increased glucagon increases hepatic glucose production, which can lead to hyperglycemia." (PMID 34199839, 2021). "Inhibition of DPP-4 is a novel therapeutic option to raise the concentration of active GLP-1 and extend its activity to improve hyperglycemia by stimulating glucose-induced pancreatic insulin secretion while inhibiting glucagon production (Mulvihill and Drucker., 2014)." (PMID 34531738, 2021). "GIP can stimulate glucagon secretion at fasting glycemic, during hypoglycemia, and hyperglycemia." (PMID 35054422, 2021). "The postprandial hyperglycemia status is defined by factors, such as the timing, quantity, and composition of the meal, carbohydrate content of the meal, and the resulting insulin production and inhibition of glucagon secretion." (PMID 34203830, 2021).
Hyperglycemia (continued). "In previous studies, we reported evidence showing that chronic cola consumption in rats impairs pancreatic storage of insulin and glucagon and produces some alterations related to metabolic syndrome (hyperglycemia and hypertriglyceridemia) with an increase in oxidative stress." (PMID 34115756, 2021). "In fact, glycogenolysis and subsequent hyperglycemia could be almost completely prevented when Fabp4 was either genetically deleted or pharmacologically neutralized, despite an intact increase in glucagon level." (PMID 34676825, 2021). "APD-elevated glucagon may therefore drive the hyperglycemic states that these drugs produce since glucagon receptor KO mice are protected against APD-induced hyperglycemia independently of changes in insulin levels." (PMID 33589583, 2021). "In parallel, APDs disrupt inhibitory α-cell D2-like receptor signaling and elevate glucagon release, resulting in hyperglycemia that may further exacerbate insulin resistance." (PMID 33589583, 2021). "Hyperglycemia may be related to a potential role of salt-inducible kinases downstream of hepatic glucagon signaling." (PMID 34160349, 2021). "A reduced Surface expression of Somatostatin-receptor-2 in islet from T2DM donors suggests somatostatin resistance, and consequently, elevated glucagon in T2DM may reflect α cell insensitivity to paracrine inhibition during hyperglycaemia." (PMID 34502413, 2021). "A key initial concern of using glucagon within a co-agonist was unwanted hyperglycaemia." (PMID 34566894, 2021). "Recent studies have clearly demonstrated that spinally-projecting C1 neurons evoke hyperglycemia by stimulating the adrenal medulla, suggesting that corticosterone and/or adrenaline could be contributing to glucagon release in this setting." (PMID 34787082, 2021). "Recent evidence shows that hyperglycaemia might impact glucagon secretion through an increased Na+ uptake." (PMID 32218947, 2020). "In addition, it is known that blood levels of compounds such as catecholamines, cortisol, glucagon, and growth hormone become elevated due to stress reactions, potentially leading to the onset of hyperglycemia." (PMID 32342247, 2020). "High dietary Se may stimulate overexpression of glutathione peroxidase-1 (GPx-1) and other antioxidant selenoproteins, promoting insulin resistance and obesity or may induce the release of glucagon resulting in hyperglycemia." (PMID 32076615, 2020). "Moreover, diabetic patients frequently exhibit abnormally high postprandial glucagon release, contributing to hyperglycemia." (PMID 32156704, 2020). "Such an effect of hyperglycemia on glucagon release could be obtained experimentally in normal animals infused with glucose to obtain a chronic hyperglycemia." (PMID 32132928, 2020). "In previous studies on animal models of type 1 diabetes, the hyperglucagonemia observed was directly coupled to the presence of hyperglycemia, the magnitude of which was decreased by the suppression of glucagon, while infusion of exogenous glucagon restored the hyperglycemia." (PMID 33294459, 2020). "However, it has been recently postulated that prior to the destruction of beta-cells in diabetes type I an increased glucagon concentration is observed and is attributed to hyperglycemia." (PMID 32132928, 2020). "Thus, it is unlikely that ICI 118,551 inhibits hyperglycemia induced by l-sulpiride through glucagon and insulin secretion." (PMID 33339892, 2020). "In critical illness, however, although plasma glucagon, cortisol, and catecholamines are elevated, concomitant hyperinsulinemia and hyperglycemia may suppress ketogenesis." (PMID 32867803, 2020). "Thus, leptin very efficiently ameliorated hyperglycemia in this new model of type 1 diabetes, probably through lowered hepatic glucose production resulting from lowered glucagon levels." (PMID 31743040, 2020). "Our data suggest that glucagon signaling does not drive hyperglycemia in insulin-deficient mice lacking LEPRs in RIP-Cre25Mgn administered i.c.v. leptin." (PMID 33071988, 2020).
Hyperglycemia (continued). "Hence, the paradoxical induction of glucagon secretion is due to direct effects of hyperglycemia in the alpha-cell and it is exacerbated indirectly by loss of beta-cells, when the inhibitory paracrine effect of insulin is lost." (PMID 32132928, 2020). "GLP-1 receptor agonists (GLP-1RAs), a new type of hypoglycemic drug, can not only increase insulin secretion, suppress appetite, and control weight by activating GLP-1 receptors, they can also control hyperglycemia by inhibiting glucagon secreted by islet α cells." (PMID 33194785, 2020). "Prolonged fasting increases stress, combined with surgical trauma, leads to increased glucocorticoids and glucagon, reduces insulin sensitivity, and reduces utilization of glucose in peripheral tissues, ultimately leading to postoperative hyperglycemia and increased insulin resistance." (PMID 32219135, 2020). "Through neural pathways as well as via receptor-mediated effects, GLP-1 reduces postprandial hyperglycemia by stimulation of insulin secretion, suppression of glucagon release, inhibition of gastric emptying and small intestinal peristalsis, and induction of satiety which limits meal size." (PMID 32356231, 2020). "The glucagon levels before surgery were significantly higher in patients with hyperglycaemia than in euglycaemic subjects with acromegaly, and the levels decreased significantly after surgery in both the groups in parallel to the significant reduction in IR and GH/IGF-1 levels." (PMID 30948746, 2019). "Additionally, acute glucagon agonism in rodents shows improved glucose tolerance and improved glucose-stimulated insulin secretion after initial glucagon-induced hyperglycemia." (PMID 31284506, 2019). "Hence, pairing glucagon and thyroid hormones as a peptide-drug conjugate provides efficacious management of multiple elements in the metabolic syndrome, including hyperglycemia, obesity, fatty liver disease, and atherosclerosis." (PMID 31091786, 2019). "Although it could be expected that the main adverse effect of glucagon therapy would be hyperglycemia, actually the central side effect of the administration of this hormone is nausea and vomiting." (PMID 31019244, 2019). "Furthermore, intravenous infusion of glucagon leads to a transient hyperglycemia in rats, and this transiency is abolished when simultaneously blocking hypothalamic glucagon signaling." (PMID 31133864, 2019). "We propose a model that explains the dysregulation of glucagon secretion induced by hyperglycemia." (PMID 30415925, 2019). "However, once hyperglycemia had presented, glucagon secretion at 1 mM glucose was reduced by 60% and elevation of glucose exerted no further inhibitory effect." (PMID 30415925, 2019). "We hypothesized that the dysregulation of glucagon secretion in the Fh1βKO mice is a consequence of hyperglycemia." (PMID 30415925, 2019). "Such a mechanism does not exclude a further role for cAMP in the paracrine regulation of glucagon release, which may become dominating during hyperglycaemia." (PMID 30953108, 2019). "Particular attention was given to the relationship between insulin and glucagon, in an attempt to determine how glucagon may be suppressed during periods of hyperglycemia." (PMID 31829209, 2019). "We observed that p52 knockdown attenuated glucagon-stimulated hyperglycemia." (PMID 31541100, 2019). "Interestingly, the raised serum glucagon levels are sub-optimal which prevents classical glucagon mediated effects like decreased feed intake and hyperglycaemia in these animals." (PMID 30505271, 2018). "Typical phenotypes of growth retardation, persistent hyperglycemia, decreased number of insulin-producing β cells, increased number of glucagon-producing α cells, and diabetic complications including diabetic nephropathy, hepatopathy, myopathy and cardiomyopathy were identified in this rabbit model." (PMID 29950431, 2018). "However, chronic hyperglycemia disrupts this fine regulation and results in elevated glucagon secretion." (PMID 30713523, 2018).
Hyperglycemia (continued). "The bihormonal hypothesis was supported by studies that showed that suppression of glucagon with somatostatin limited the hyperglycaemia seen in patients with type 1 diabetes and alloxan-diabetic dogs." (PMID 29412829, 2018). "The question remained, however, as to how to harness these effects of glucagon without causing harmful hyperglycaemia." (PMID 29412829, 2018). "Enhanced release of glucagon, glycogenolysis, and peripheral insulin resistance may explain hyperglycemia in Crhr2 null mice." (PMID 30400826, 2018). "These new findings suggest that co-administration of OCT and PAS may avoid the induction of hyperglycemia by PAS by decreasing serum glucagon levels." (PMID 28542433, 2017). "With long-acting agonists, however, most of the decrease in postprandial glycemia probably results from the decrease in preprandial glycemia—the main component of postprandial hyperglycemia—and the glucagon suppression that is common to all GLP-1 receptor agonists." (PMID 28115994, 2017). "This supported the general concept regarding the role of glucagon in contributing to hyperglycemia but also indicated that there may be a minimal insulin requirement for glucagon antagonism to be effective." (PMID 28323959, 2017). "If glucose metabolism in α- and β-cells controls glucagon and insulin release in hypo- and hyperglycaemia, respectively, it might be reflected by a relatively left-shifted dependence of metabolism on the glucose concentration in the α-cell." (PMID 27044660, 2016). "It has been suggested that the hyperglycemia may be due to the different inhibitory effects of pasireotide on pancreatic α- and β-cells, which produce glucagon and insulin, respectively (52, –, 54)." (PMID 26990064, 2016). "We report that the absence of hyperglycemia observed in glucagon-deficient mice after STZ treatment can be explained through the persistence of a residual β-cell mass, which ensures a low level of insulin action." (PMID 27092792, 2016). "However, the involvement of these factors in direct control of glucagon secretion in hyperglycaemia is also questionable." (PMID 27044660, 2016). "In turn, increased glucagon levels may drive an increased rate of gluconeogenesis and glycogenolysis, contributing to hyperglycemia." (PMID 28702245, 2016). "We found that GcgKO mice developed marked hyperglycaemia under the severe insulin deficiency caused by STZ-induced beta cell destruction despite the absence of glucagon." (PMID 27053237, 2016). "Collectively, these findings demonstrate that a total absence of glucagon action is not sufficient to prevent hyperglycemia in case of severe insulin deficiency." (PMID 27092792, 2016). "Given how SST plays a major role in the homeostasis of glucose metabolism, inhibiting the release of insulin, glucagon, and incretins, along with the fact that hyperglycemia is a known side effect of the administration of somatostatin analogues, this was somewhat surprising." (PMID 27399347, 2016). "Individuals with post-prandial hyperglycaemia exhibit decreased insulin secretion after food consumption and less inhibition on the release of glucagon, leading to aberrant hepatic and renal glucose production, reduced glucose uptake by cells and consequently elevated blood glucose levels." (PMID 26308010, 2015). "An increased level of dietary selenium intake may increase the release of glucagon, which can lead to hyperglycemia." (PMID 25880386, 2015). "Thus, glucagon remains inappropriately elevated in hyperglycemia at comparable levels of blood glucose." (PMID 25993052, 2015). "Hyperglycemia may also be the result of excessive glucagon secretion by pancreatic α cells, which leads to an increase in gluconeogenesis." (PMID 25574213, 2015).
Hyperglycemia (continued). "Several studies have demonstrated significant blood glucose lowering effects in diabetic animal models through application of potent peptide antagonists, and immunoneutralization of glucagon in diabetic animals has been shown to reduce glucagon-stimulated hyperglycemia." (PMID 26236379, 2015). "Chronic hyperglycaemia is associated with a dramatic reduction in insulin-positive cells and an increase in glucagon-positive cells in islets, without alterations in cell turnover." (PMID 25145789, 2014). "An increase in glucagon activity contributes to hyperglycemia in obesity." (PMID 24740421, 2014). "Hyperglycemia (HG) and insulin resistance are the hallmarks of a profoundly altered metabolism in critical illness resulting from the release of cortisol, catecholamines, and cytokines, as well as glucagon and growth hormone." (PMID 24899891, 2014). "We used lineage tracing to test whether β-cells start to express glucagon when exposed to chronic hyperglycaemia." (PMID 25145789, 2014). "Since both decreased insulin and increased glucagon secretion from pancreatic islets are known to contribute to hyperglycemia in patients with T2D, we investigated whether the identified candidate genes also affect glucagon secretion in clonal α-cells." (PMID 24603685, 2014). "Activated GLP-1 neurons of the NTS also project to the ARC to modulate vagal motor outflow to the pancreas and other tissues not depicted, increasing insulin secretion from the β-cells in states of hyperglycemia and suppresses glucagon from the α-cells, leading to lowering of blood glucose." (PMID 24795698, 2014). "They stated that high-Se diets may stimulate the release of glucagon, promoting hyperglycemia, or induce overexpression of glutathione peroxidase-1 and other antioxidant selenoproteins resulting in insulin resistance and obesity." (PMID 24555483, 2014). "Glucagon-mediated hyperglycemia may be attenuated by liraglutide treatment, but glucagon level was not monitored in present study." (PMID 25237400, 2014). "This hyperglycemia stimulates insulin release and inhibits glucagon liberation." (PMID 25250626, 2014). "Together, our functional data propose a model where identified candidate genes may contribute to hyperglycemia in T2D patients by both lowering insulin and increasing glucagon secretion from pancreatic islets." (PMID 24603685, 2014). "However, glucagon affects glucose metabolism mainly by inducing glycogen breakdown and glucose-6-phosphatase on one hand whereas, on the other hand glucagon contributes the hyperglycemia by inhibiting the enzyme pyruvate kinase." (PMID 24993916, 2014). "In conclusion, the anesthetic xylazine can cause acute hyperglycemia with no significant alterations of blood insulin, glucagon, and GLP-1 in normoglycemic and insulin-dependent diabetic non-human primates." (PMID 24138083, 2013). "Thus, exenatide increases insulin production and secretion in response to hyperglycaemia, suppresses inappropriate plasma glucagon secretion, slows gastric emptying and decreases hepatic glucose production, all of which combine to lower blood glucose." (PMID 23061886, 2012). "In addition to increased α-cell sensitivity to insulin, chronic hyperglycemia plays an important role in dysregulation of α-cells but no effective treatment has been developed to increase (or regulate) glucagon secretion to combat hypoglycemic attacks." (PMID 22969729, 2012). "Defects in the insulin-glucagon fine-tuning machinery may result in β-cell glucose incompetence, leading to unsuppressed glucagon secretion and subsequent hyperglycemia, which often occur under extreme conditions of glucose influx or efflux." (PMID 23316165, 2012). "Beta-cell dysfunction has been identified as the main cause by which TCF7L2 variants may exert their effects on glucose metabolism, and rs7903146 may impair the ability of hyperglycemia to suppress glucagon." (PMID 22916254, 2012).